JAK1 (Janus kinase 1)
Diseases named in the same sentence as JAK1 in open-access papers (continued):
Sharing a sentence is not in itself a finding about the gene and the disease.
cancer (277 papers, 2002 to 2026). A tumor composed of atypical neoplastic, often pleomorphic cells that invade other tissues. "HOXA10 has been implicated in the deregulation of multiple cancer types via activation of the JAK1/STAT3 signaling pathway." (PMID 40612864, 2025). "Spatial transcriptomics delineated the molecular variant expressions of hub gene JAK1 in malignant cells across cancers, while immunohistochemistry validated the differential protein levels of JAK1 in NB." (PMID 39703515, 2024). "The Cancer Dependency Map (DepMap) results showed that CHMP7 is associated with ES cell growth, and the Gene Set Cancer Analysis (GSCALite) results revealed that the JAK1 mutation frequency was the highest." (PMID 37663658, 2023). "Loss-of-function JAK1 mutations occur at high frequency in cancers with MSI and represent a potential pancancer adaptation of immune evasion." (PMID 37461056, 2023). "Our analysis revealed candidate GOF variants in the JAK1 pseudokinase domain with clinical precedence in cancer." (PMID 36669486, 2023). "IFN signaling in cancer cells is necessary for the response to immunotherapies, and loss of JAK1/2 or of IFN-inducible MHC I genes frequently accounts for therapy resistance." (PMID 38304252, 2023). "In immunogenic mouse models, cancer cell JAK1 loss abrogates the effect of dual checkpoint blockade and focal irradiation and inhibits the antitumor effect of adoptive transfer of antigen-specific T cells." (PMID 37565053, 2023). "Upon treatment with Tam, the ligand-inducible CreERT2 recombinase facilitated the conversion of the floxed Jak1 into a knockout allele in the two cancer cell lines where Flp had correctly recombined the Rosa26CAG-FSF-CreERT2 locus (lower)." (PMID 34675248, 2021). "The results of this feasibility study show that it is possible to delete both alleles of Jak1 in cancer cells with high efficiency in a tamoxifen-inducible manner." (PMID 34675248, 2021). "Constitutive activation of the JAK1/STAT3 pathway is frequently observed in cancer cells while JAK2/STAT3 is closely associated with cytokine expression, cell apoptosis, and proliferation." (PMID 32895373, 2020). "For example, in our trial, 60% (6 of 10 MMRD patients) harbored JAK1 frameshift mutations involving the hotspot K860/P861 position compared with only 14.8% of patients with MMRD cancers in the TCGA EC data set." (PMID 32494760, 2020). "Results indicated that JAK1 expression was closely associated with cancer stage and nodal metastasis." (PMID 33323549, 2020). "Overall, 70% of patients (7 of 10) exhibited frameshift JAK1 mutations in our trial compared with only 23.8% of patients with MMRD cancers in the TCGA EC data set." (PMID 32494760, 2020). "Previous studies have reported that JAK1 is highly associated with tumorigenesis and plays important roles in the proliferation, differentiation, and apoptosis of cancer cells." (PMID 33323549, 2020). "Increasing evidence has suggested that functional SNPs of JAK1 gene is linked to inflammation and cancer.Several nsSNPs of JAK1 gene are known." (PMID 31831954, 2019). "Somatic mutations in JAK1/2 have been proposed as a mechanism of evasion to immune recognition, leading to both primary and acquired resistance to PD-1 blockade in some cancer patients." (PMID 31221207, 2019). "From these data, we derived two primary conclusions: 1) JAK1 frameshifts are loss of function alterations that represent a potential pan-cancer adaptation to immune responses against MSI tumors." (PMID 29121062, 2017). "STAT3 is predominantly activated by IL-6 receptor via JAK1/2 in cancer cell lines in association with transcriptional silencing of SOCS-1 by hypermethylation." (PMID 26491227, 2015). "These polymorphisms are of particular interest as they may influence JAK1's role in cytokine signaling, a pathway implicated in the pathogenesis of various cancers, including HCC." (PMID 40344393, 2025).
cancer (continued). "Specifically, 53% (n = 9/17) had no previously reported driver of resistance, and 35% (n = 6/17) had a mutation in a gene previously implicated in acquired resistance (B2M or JAK1/2) that was expected to be deleterious and changed in cancer cell fraction (CCF)." (PMID 39933900, 2025). "Among the PPI proteins, six kinases were found to be associated with cancer pathways, including mTOR complex 1 (mTORC1), Janus kinase 1 (JAK1), Activin receptor type 1C (ACVR1C), Phosphorylase kinase catalytic subunit gamma 1 (PHKG1) and mitogen-activated protein kinase 4 (MAPK4)." (PMID 37355516, 2023). "For example, cancers with high mutational burden have JAK1 loss-of-function mutations." (PMID 37047778, 2023). "JAK1 plays a significant role in the intracellular signaling by interacting with cytokine receptors in different types of cells and is linked to the pathogenesis of various cancers and in the pathology of the immune system." (PMID 35529449, 2022). "This appeared partly due to enrichment of JAK1 truncating frameshift mutations, which were associated with reduced IFNγ response in human cancers, loss of IFN signalling in cell lines, and which have recently been shown to predict lack of response to immunotherapy in EC." (PMID 35262923, 2022). "The equivalent of the JAK2 V617F mutation in JAK1 (JAK1 V658F) has been linked with other cancers." (PMID 31683831, 2019). "JAK1 gene mutations are hypothesised as initial molecular defects in human cancer andautoimmune diseases." (PMID 31831954, 2019). "JAK1 frameshifts occurred in MSI-H cancers with high mutational burdens." (PMID 29121062, 2017). "Thus, JAK1 frameshifts are a likely pan-cancer alteration that occur primarily in MSI-H cancers with high mutational burden." (PMID 29121062, 2017). "Thus, JAK1 frameshift mutations are a potential pan-cancer adaptation to the immune response that occurs against highly mutated MSI-H tumors." (PMID 29121062, 2017). "Thus, IAP’s pro-oncogenic activity could be enhanced by the loss of its bound LKB1 in LKB1 mutant cancer, while JAK1 could be directly weakened by IAP interaction, leading to STING suppression and immune resistance." (PMID 40057483, 2025). "Inhibitors of JAK1/2 or HIF1α or drugs targeting their downstream signaling pathways have great potential for cancer therapy." (PMID 41520505, 2026). "UBA1 is a potential cancer biomarker and therapeutic target that mediates immune evasion through JAK1 degradation, and targeted UBA1 inhibition synergizes with immune checkpoint blockade to enhance antitumor immunity and survival." (PMID 39540840, 2025). "As a selective JAK1 inhibitor, upadacitinib affects T and NK cells, which are critical for immune surveillance and cancer detection." (PMID 40666511, 2025). "Multi-transcriptome analyses using clinical samples revealed that PROC exhibited an activated Janus kinase (JAK)/signal transducer and activator of transcription pathway with high JAK1 expression in cancer cells." (PMID 40883550, 2025). "TAM produce IL‐10 which improves the viability of cancer cells in NSCLC by stimulating the JAK1/STAT1/NF‐κB/Notch1 signaling pathway and promoting the expression of SOX‐2 and other genes linked to cancer cells." (PMID 39927632, 2025). "Previous studies have demonstrated that chemotherapy activates NF-κB via the AKT-IκB pathway and STAT3 via the IL-6R/JAK1 pathway, leading to PD-L1 expression and contributing to chemotherapy resistance in cancer cells." (PMID 40999385, 2025).
cancer (continued). "The unique activation of IFNγ-JAK-STAT signaling in cancer cells following arginine deprivation prompted us to examine the potential therapeutic effect of the JAK1/2 inhibitor ruxolitinib." (PMID 41511309, 2025). "JAK1 expression was higher in cancer cells within PROC tissues where data on its expression levels were available for analysis." (PMID 40883550, 2025). "Numerous studies have demonstrated that JAK1-related signaling pathways exhibit significant Anti-cancer efficacy." (PMID 40746612, 2025). "JAK1, along with JAK2, JAK3, and TYK2, are members of this family and are implicated in both inflammatory disorders and cancer." (PMID 39744421, 2025). "The JAK1/TLR3/PRMT5/c-Myc axis provides potential targets for cancer and reasonable evidence for predicting chemotherapeutic efficacy and patients' prognosis." (PMID 40675966, 2025). "DFT calculations further revealed that 5b had the lowest calculated energy values; -4.89 eV (HOMO) and − 3.22 eV (LUMO), and the energy gap was found to be 1.66 eV, supporting its role in JAK1 inhibition and cancer cell adhesion reduction." (PMID 40542057, 2025). "Ultimately, we explore the biological function of the hub gene JAK1 in pan-cancer multi-omics landscape." (PMID 39703515, 2024). "EC shows an exceptionally high frequency of loss-of-function mutations in JAK1, a key mediator of IFN-γ signaling, in comparison to other cancer types." (PMID 38383447, 2024). "Although overcoming resistance remains a significant challenge, promising strategies involve the use of agents that inhibit innate immune responses in cancer cells, such as ruxolitinib (JAK1/2 inhibitor)." (PMID 39861805, 2024). "The enhanced expression of cytokines and their receptors mainly result in the aberrant regulation of JAK1/2, STAT1, STAT3, STAT5, and STAT6, causing inflammation and cancer development, cancer recurrence, and decreased overall survival." (PMID 38094755, 2023). "THU inhibits CDA activity, and the combined THU and decitabine treatment of cancer cells was similarly effective in inhibiting JAK1." (PMID 37208732, 2023). "Janus kinase 1 (JAK1) plays a critical role in most cytokine-mediated inflammatory, autoimmune responses and various cancers via the JAK/STAT signaling pathway." (PMID 37641144, 2023). "RAB1A overexpression promotes cancer cell migration, invasion, and metastasis by activating JAK1/STAT6 signaling." (PMID 37370041, 2023). "IL-6/JAK1/STAT3 signaling has been recognized as a key mechanism for cancer drug resistance and cancer stemness." (PMID 37440925, 2023). "The role of JAK1 is highly dependent on the cell conditions and can vary across different cancer subtypes." (PMID 35620468, 2022). "Loss of LXN in macrophage activates JAK1/STAT3/PD-L2 pathway, which contribute to the immune escape of cancer cells by attenuating the function of T cells in TME." (PMID 36323670, 2022). "JAK inhibitors, which have been authorized for the treatment of cancer and autoimmune illnesses, have provided the first insight on the importance of JAK1 in NK cell biology." (PMID 35529449, 2022). "The JAK1/STAT1 pathway is the canonical cytokine-induced signaling that is constitutively active in cancer cells." (PMID 35997090, 2022). "JAK1 was known to drive cancers with microsatellite instability (MSI) and was often seen in mismatch repair deficient (MMRD) PDAC." (PMID 35698045, 2022). "Recently, JAK1 inhibitors have been investigated in many clinical trials against cancers, but have achieved only moderate efficacy when applied as monotherapies due to undesired systemic side effects." (PMID 33523587, 2021). "In this study, we found that PI3K/AKT/mTOR inhibitors upregulated MIF expression and secretion in several PTEN-deficient cancer cells, and activated STAT3 activity through JAK1, eventually limiting the effects of these inhibitors." (PMID 33431808, 2021). "The activation of IL4Rα/IL13Rα1 by IL4/IL13 stimulates JAK1/JAK2/JAK3-STAT6-mediated proliferation of cancer cells." (PMID 33419470, 2021).
cancer (continued). "JAK/STAT signaling has been described as one of the major signaling pathways aberrantly activated in EOC and inhibition of JAK1 by small molecule inhibitors was shown to suppress cancer progression of EOC and other cancer types." (PMID 34359703, 2021). "The IL‐6/JAK1 pathway was reported to drive PD‐L1 Y112 phosphorylation to promote cancer immune evasion." (PMID 33523587, 2021). "β-Caryophyllene, β -caryophyllene oxide, and α-humulene, have been also found to induce apoptotic cancer cell death through the regulation of different pathways, such as JAK1/STAT3, NF-kB and PI3K/AKT/mTOR/S6K1." (PMID 34771097, 2021). "Migration of epithelial carcinoma cells can be promoted through multiple core cancer pathways, including the JAK1/2-STAT3/5, β-Catenin/WNT, RAS/RAF-ERK1/2 or TGF-β/SMAD2/3 pathways." (PMID 33465556, 2021). "Through Pearson’s correlation coefficient analysis (|R2|> 0.3 and P< 0.05), 206 transcription factors were associated with cancer driver gene expression, and DDX3X, JAK1, EGR2, IKZF3, and CCR7 were the five most enriched cancer driver genes." (PMID 34507558, 2021). "To further assess the expression of JAK1 in multiple malignancies, we analyzed the expression levels of JAK1 mRNA in various types of cancer using the UALCAN database." (PMID 33323549, 2020). "Another significant clinical feature was the influence of nodal metastasis and individual cancer stages on JAK1 expression." (PMID 33323549, 2020). "In this study, by virtual screening, we identified and validated a novel JAK1/2 inhibitor AH057 that exhibited most potent antitumor efficacy against CC cells over other cancer cells." (PMID 32895373, 2020). "More importantly, we also provided evidence that a strategy of combining with JAK1/2 inhibitor ruxolitinib sensitizes cancer cells to paclitaxel treatment." (PMID 33042272, 2020). "Iron directly binds CDK1, which is upregulated in several cancers, thereby promoting JAK1 phosphorylation and activation of STAT3 signaling to promote colorectal carcinogenesis." (PMID 30931929, 2019). "T-cells specific against two mutated cancer-associated genes, NUP214 and JAK1, recognized autologous tumors." (PMID 31221207, 2019). "Previous studies have reported that IL-6 or IL-6 downstream signaling confers chemotherapeutic resistance by triggering the PI3K/Akt, MAPK/ERK, or Jak1/STAT3 signaling pathway in cancer cells." (PMID 30927911, 2019). "In interferon-γ-treated cancer cells, cytoplasmic HSP90α acts as a chaperone protecting JAK1/2 from degradation and thus enhances STAT-1 phosphorylation and the downstream gene expressions." (PMID 31847880, 2019). "IFN-γ, secreted by CD4+ T-cells, interacts with its receptors on the cancer cell surface and induces tyrosine phosphorylation of Jak1 and Jak2." (PMID 29796172, 2018). "And in vitro truncating mutations of JAK1 and JAK2 results in insensitivity to IFNγ and its antiproliferative effects on cancer cells." (PMID 30294272, 2018). "Mutations in other cancer genes including CBFB, IDH1, JAK1, KMT2A, SMAD4, and SMARCA4 were found in one MBC each." (PMID 29214215, 2017). "By exome sequencing, we identified novel, frequent frameshift mutations in four cancer-critical genes (CRTC1, BCL9, JAK1, and PTCH1)." (PMID 28539123, 2017). "These experiments implicate JAK1/3 signaling in cancer- and MI-mediated diaphragm weakness in mice, and provide a compelling case for further investigation." (PMID 26864813, 2016). "This approach identified candidate variants in known cancer genes, including in BCOR, NOTCH2, TET2, NF1, EZH2, and JAK1." (PMID 28721364, 2015). "At the moment, more studies are needed to establish the overall impact of interference with JAK1/2 signaling in cancer therapy." (PMID 28548066, 2014). "In addition, targeting the crosstalk between JAK1/2 and HIF1α has been shown to be a promising strategy for cancer treatment." (PMID 41520505, 2026).
cancer (continued). "Interestingly, on the examined cancer cell lines, they demonstrated potential as dual inhibitors of JAK1 and CDK7." (PMID 41530217, 2026). "Furthermore, we analyzed the mutation status of ASCC3, JAK1, NFKB1, SEMA5A, NR2C2, CNTF and CREB1 across pan-cancer." (PMID 40881169, 2025). "In addition to IFN-γ response-associated genes (JAK1, STAT1 and STAT3), CIITA, a master regulator of MHC-II gene expression, was highly expressed in MHC-II+ cancer cells." (PMID 41281745, 2025). "Additionally, mutations in JAK1 and MAPKAPK2 have been associated with various types of cancer, but their relationship with CTRP6 expression remains to be fully explored." (PMID 39979869, 2025). "Furthermore, fasting reduces the production of adenosine by cancer cells, inhibiting the activation of the JAK1/STAT pathway, thereby reducing cancer cell proliferation." (PMID 40429883, 2025). "Although the incidence remains very low, research indicates that individuals with AA who are administered JAK1 inhibitors may face a heightened likelihood of developing cancer." (PMID 40860887, 2025). "Janus Kinase 1 (JAK1) plays a crucial role in cancer progression." (PMID 38893126, 2024). "In addition, the monoclonal anti-IL-6R antibody tocilizumab increases apoptosis in cancer cells through the IL-6/Jak1/STAT3 axis, promoting tumorigenesis, invasion and antiapoptotic proteins expression in gastric cancer." (PMID 39075612, 2024). "Furthermore, we conducted pan-cancer spatial transcriptomics analysis to comprehensively explore the expressions of JAK1 in malignant cells and malignant spots." (PMID 39703515, 2024). "IFN-γ induces the expression of PD-L1 in cancer cells through JAK1/2–STAT1/2/3–IRF1 pathway." (PMID 38802348, 2024). "This allowed for the first time the identification of mutations associated with acquired resistance to ICB and shown loss of function mutation in IFN signaling (Janus kinase-1 and 2) in two patients and beta-2-microglobulin (B2M) in a third patient in ICB resistant cancer lesions." (PMID 37180110, 2023). "JAK1 is a critical molecule linking IFNγ receptor activation to activation of all IFNγ-sensitive genes and loss of JAK1 downregulates class II, class I, and CXCL9/10 in cancer cells." (PMID 37565053, 2023). "Moreover, activation of the IL-6/JAK1 axis enhanced PD-L1 phosphorylation by Janus kinase 1 to promote cancer immune evasion." (PMID 36980527, 2023). "A prognostic role of LIFR and its ligand (LIF) has been recognized across several human cancers, but the importance of this pathway and its co-occurrence with a JAK1 mutation have never been explored in lymphoid malignancies." (PMID 37287455, 2023). "Moreover, JAK1 expression in cancer cells allows individual cells to contract, perhaps enabling them to transcend their tumor and spread to other areas of the body." (PMID 35529449, 2022). "The IL-6/JAK1 pathway induces PD-L1 Y112 phosphorylation, leading to cancer immune evasion." (PMID 36479088, 2022). "The involvement of the IFN-γ/Jak1/STAT1 signaling pathway in ferroptosis therefore provides additional opportunities for cancer therapy, as some reagents targeting this pathway could be applied." (PMID 35399527, 2022). "Low concentrations of IFN-γ boost CSC stemness through the activation of the PI3K/AKT/NOTCH1 pathway, whereas high levels of IFN-γ induce cancer cell apoptosis through the janus kinase 1 (JAK1)/signal transducer and activator of transcription 1 (STAT1)/caspase pathway." (PMID 36032082, 2022). "In addition, miR-769-5p inhibits cancer cell progression in OSCC by directly targeting the JAK1/STAT3 pathway." (PMID 36139534, 2022).